FAM221A (family with sequence similarity 221 member A)
Synonyms: C7orf46; FLJ45875; MGC72075; DKFZp686F0810
Tractability: PROTAC: ubiquitination databases record sites on it.
Gene: Protein-coding gene on chromosome 7 (23,680,114 to 23,703,249, forward strand). Ensembl gene ENSG00000188732.
Subcellular location (Human Protein Atlas): Cytosol
Gene Ontology:
Molecular function: protein binding
Genetic constraint (gnomAD): Loss-of-function variants: 22 observed, 19.6 expected, observed/expected ratio (o/e) 1.12, 90% interval 0.8 to 1.6. The upper end of that interval is the gene's LOEUF score, 1.6, which puts it in group 6 of 6, group 1 being the genes least tolerant of losing a copy. Missense variants: 260 observed, 247.6 expected, observed/expected ratio (o/e) 1.05, 90% interval 0.95 to 1.16. Synonymous variants: 103 observed, 93.64 expected, observed/expected ratio (o/e) 1.1, 90% interval 0.94 to 1.3.
Homologues: Orthologues: chimpanzee FAM221A (98% identical), guinea pig FAM221A (88% identical), rat Fam221a (83% identical), mouse Fam221a (83% identical), macaque FAM221A (82% identical), pig FAM221A (81% identical), tropical clawed frog fam221a (65% identical), zebrafish fam221a (41% identical). Paralogues in human: FAM221B (19% identical).
Diseases named in the same sentence as FAM221A in open-access papers:
FAM221A is named in the same sentence as 6 diseases in open-access papers, as found by Europe PMC text mining. Sharing a sentence is not in itself a finding about the gene and the disease. The quoted sentences say what the papers report.
dementia (1 paper, 2017). Loss of intellectual abilities interfering with an individual's social and occupational functions. "Targeted re-sequencing of the six candidate genes (LTF, MME, UBE4A SORL1, FAM221A and KDM2B) was performed in 35 EOAD cases with a family history of dementia." (PMID 28595629, 2017).
FAM221A also shares sentences with these, for which no sentence is quoted: astrocytoma (1 paper); cancer (1); genetic diseases (1); melanoma (1); tumor (1).